IFNG (interferon gamma)
Diseases named in the same sentence as IFNG in open-access papers (continued):
Sharing a sentence is not in itself a finding about the gene and the disease.
autoimmune disease (continued). "Interferon γ (IFNγ) is a dimerized soluble cytokine, and aberrant IFNγ expression is related to a number of inflammatory and autoimmune diseases." (PMID 32019180, 2020). "There are several lines of evidence that Th1 cells producing IFNγ are closely correlated with the clinical severity of autoimmune diseases and can independently transfer diseases into naïve mice." (PMID 33135395, 2020). "Several reports have shown that serum IFNγ is increased in patients with autoimmune diseases such as systemic lupus erythematosus (SLE) and rheumatoid arthritis (RA)." (PMID 33379198, 2020). "IL-18 and IL-12 synergistically stimulate the production of interferon gamma (IFNγ) by T lymphocytes and NK cells altering the transcription of more than 30 genes to elicit a number of inflammatory and autoimmune diseases." (PMID 33228660, 2020). "The anti-inflammatory cytokine IFNγ (Interferon gamma) is an extensively studied marker used to follow T-cells reactivity after immunomodulation treatment, autoimmune-diseases, and T-cell malignancies." (PMID 33224151, 2020). "Collectively, our data support the primary role for IFNγ in linking obesity to the development of autoimmune diseases." (PMID 33379198, 2020). "Aberrant IFNγ expression was observed in other autoimmune disease murine models, including experimental autoimmune encephalomyelitis and collagen-induced arthritis, in both protective and detrimental roles." (PMID 33379198, 2020). "TNF and other pro-inflammatory cytokines, such as interferon γ (IFNγ) and interleukin 1 (IL-1), determine the disease onset, severity, and relapse of autoimmune diseases and affect the efficacy of treatment, including MSC-based therapy." (PMID 30079066, 2018). "Kantarci and colleagues have discussed the possible use of anti-interferon gamma antibodies in the treatment of patients with autoimmune diseases." (PMID 29257064, 2017). "IP-10 is induced by interferon gamma and involved in many inflammatory diseases such as chronic inflammatory arthritis, autoimmune diseases, type 1 diabetes, cardiovascular disease, psoriasis...etc." (PMID 28926588, 2017). "Of relevance, two of these genetic patterns are significantly enriched in genes from immune response pathways that are crucial for this group of autoimmune diseases: TNFα and IFNγ cytokine pathways." (PMID 28982122, 2017). "The extracts of Brazilian propolis were benefited to control the unbalanced cytokine networks of Th1 cells via suppressing the differentiation of Th1 cells and the generation of IFNγ-producing CD4 T cells in an autoimmune disease model." (PMID 28344896, 2016). "We included IFNγ-related autoimmune diseases as positive controls, as we used this cytokine to promote pro-inflammatory macrophage activation." (PMID 27796300, 2016). "PsO is a chronic, inflammatory, T-cell-mediated autoimmune disease that results from activation of inflammatory cytokines (interferon gamma, TNFα, IL-12, IL-23) and presents with erythematous scaly plaques in 1% to 3% of Caucasians." (PMID 28492015, 2016). "These qPCR results are consistent with the observed decrease in IFNγ (T‐bet) and IL‐17 (RORC) secretion levels and are particularly interesting as several investigations have associated IL‐21 to autoimmune diseases." (PMID 26762709, 2016). "While MS is traditionally thought to be a Th1-cell mediated autoimmune disease, characterized by IFNγ inflammation, recent work has demonstrated that other T cell subsets also contribute to the development of MS." (PMID 25962726, 2015). "The potent proinflammatory activities of IFNγ combined with its inhibitory potential on Th2 cells make IFNγ a central mediator of Th1 mediated autoimmune disorders." (PMID 25614713, 2014). "T cells expressing IL-17/IFNγ are found in the context of IL-17-dependent autoimmune diseases and IL-23 is necessary to sustain the IL-17/IFNγ phenotype." (PMID 25253467, 2014).
autoimmune disease (continued). "Because IL-18 can increase IFNγ production, blocking IL-18 activity in autoimmune diseases is an attractive therapeutic target since anti-IL-12/23 reduces the severity of Crohn’s disease as well as psoriasis." (PMID 24115947, 2013). "Regulatory T cells (Tregs) play an indispensable role in the prevention of autoimmune disease, as interferon gamma (IFNγ) mediated, lethal auto-immunity occurs (in both mice and humans) in their absence." (PMID 24391643, 2013). "In autoimmune disease some of the protective effects mediated by IFNγ seem to be due to its capacity to induce iNOS expression." (PMID 22973278, 2012). "Given the increased susceptibility of women to MS and the significance of IL6 in the autoimmune process compared to IFNγ, it is logical to assume that IL6 pathways are in some way implicated in the prevalence of autoimmune diseases in women." (PMID 23148845, 2012). "The data confirm our belief that sexual dimorphism in autoimmune diseases is the result of differing pathways that regulate Th cell network homeostasis: interleukin (IL) 6 pathways in women and IFNγ pathways in men." (PMID 23148845, 2012). "Since women are more susceptible to MS disease and the IL6 has a more significant role in the autoimmune process compared to IFNγ, it is logical to assume that IL6 pathways are in some way implicated in the prevalence of autoimmune diseases in women." (PMID 23148571, 2012). "Additionally, the ligand-receptor pairs associated with Trm cells, such as MIF-CD74 and IFNG-IFNGR, are known to contribute to autoimmune disease pathogenesis." (PMID 41188893, 2025). "The contribution of DN T cells to the pathogenesis of autoimmune diseases depended upon a proinflammatory phenotype, and the secretion of proinflammatory lymphokines, like IL‐1 β, IL‐17, and IFNγ, and possibly autoreactive TcRs that strongly bind amino acid residues on HLA molecules." (PMID 41416941, 2025). "TIM3, a member of the T cell immunoglobulin and mucin domain (TIM) family, was initially identified on the surface of interferon gamma (IFNγ)-producing T helper type 1 (Th1) cells and is involved in macrophage activation and the regulation of autoimmune diseases." (PMID 40969278, 2025). "The platform was optimized for Interferon-gamma (IFNγ) detection, a common biomarker for M. tuberculosis infection and autoimmune diseases, using an immunofluorescence assay, achieving an impressive 500fg/mL limit of detection, outperforming that of ELISA, 2pg/mL." (PMID 38534237, 2024). "Both atherosclerosis and autoimmune diseases are driven by inflammatory processes, and research has shown that proinflammatory cytokines such as tumor necrosis factor-alpha (TNFα) and interferon-gamma (IFNγ) can synergistically induce RNF213 expression, leading to angiogenesis in vitro and in vivo." (PMID 39857601, 2024). "IFNγ is involved in the immune regulation of several autoimmune diseases, including pSS." (PMID 38406824, 2024). "Altogether, IFNγ 2, SAMHD1 8 and Klotho 23 have been implicated in autoimmune diseases." (PMID 37213666, 2023). "IFNγ is a major cytokine that profoundly affects the pathogenesis of autoimmune diseases." (PMID 37213666, 2023). "Shared IFNγ-dependent processes are central for the pathogenesis of autoimmune diseases." (PMID 36425763, 2022). "Indeed, IFNγ has emerged as a therapeutic target in several autoimmune diseases, and the present work highlights the possibility of employing IFNγ as a therapeutic target in immune diseases." (PMID 35625832, 2022). "Overexpression of IFNγ is also observed in a number of autoimmune diseases." (PMID 34639073, 2021). "Anomalous autoreactive responses of CD4+ T helper cells, such as Th1 cells producing IFNγ 2 and Th17 cells producing IL‐17,47, 48, 49, 50, 51, 52 are tightly correlated with the clinical severity and progression of several autoimmune diseases, clinically and experimentally." (PMID 33135395, 2020).
autoimmune disease (continued). "A previous study reported that mice receiving an adoptive transfer of M(IFNγ+LPS+IC) produced a high level of IL-10, resulting in decreased disease severity in autoimmune diseases such as experimental autoimmune encephalomyelitis (EAE) and reduced mortality in sepsis." (PMID 31998290, 2019). "It will be interesting to show whether PRL favors the presence of Treg IFNγ-secreting cells, especially because this has been reported for other autoimmune diseases." (PMID 26844452, 2016). "Clinicians and researchers hereby need to take into account that immune system activation involving stimulation of interferon-gamma release by T-effector cells as in autoimmune diseases like sarcoidosis or malignancies can increase urinary neopterin/creatinine ratios." (PMID 27433370, 2016). "Interestingly, there is some evidence to indicate that the ability of Th17 cells to promote pathology in autoimmune diseases is acquired when the cells gain the ability to produce IFNγ." (PMID 26101460, 2015). "MAIT cells could participate through their ability to produce IFNγ and/or IL-17, two major cytokines in the pathogenesis of several chronic inflammatory/autoimmune diseases." (PMID 26483793, 2015). "If manipulation of Th17 is safe, it would be of interest to know whether augmenting the transcription factor RUNX1 for IL-17+IFNγ+ T cell phenotype induction will be beneficial in treating patients with cancer and autoimmune diseases." (PMID 26101460, 2015). "IFNG overexpression has been reported in cutaneous LE subtypes and other autoimmune diseases." (PMID 25928531, 2014). "Interest in IFNγ/IL-10 co-producing Th1 cells has increased in recent years as these cells have been found to be important regulators of the immune response to several infectious, allergic, and autoimmune diseases." (PMID 24415936, 2014). "Furthermore, multiple groups have shown the benefits of disrupting the IFNγ signaling pathway in autoimmune disease." (PMID 25010693, 2014). "Moreover, ongoing research strategies for treatment of autoimmune diseases such a lupus include the use of antibodies targeting cytokines involved in disease progression, such as IFNγ." (PMID 24391643, 2013). "Additionally, T helper type 1 (Th1) and Th17 cells secrete proinflammatory cytokines, including IL-17 and interferon-gamma (IFN-γ), promoting inflammatory responses and contributing to various autoimmune diseases, such as multiple sclerosis, collagen-induced arthritis, and rheumatoid arthritis (RA)." (PMID 39062908, 2024). "The exhibition of the M1 phenotype by several factors (e.g., interferon-gamma, tumor necrosis factor α (TNFα), lipopolysaccharide) leads to anti-bacterial, anti-virus, and anti-tumoral activity and the induction of type II diabetes, atherosclerosis, and autoimmune disease." (PMID 37762869, 2023). "Interestingly, CXCL10 release, identified in this investigation as a robust marker of TLR7/8 immune activation, has also been shown to be part of an amplification feedback loop driven by IFNγ and TNFα release from Th1 lymphocytes in a variety of autoimmune diseases." (PMID 35261923, 2022). "Aberrant Th1 and Th17 cells could activate innate immune cells by producing proinflammatory cytokines, such as IFNγ, IL-17, and TNFα, and metformin is shown to inhibit in the production of cytokines of Th1 and Th17 cells, alleviating the autoimmune diseases including various ALIs." (PMID 34959222, 2021). "Similar to CIDP, SAPP is an autoimmune disease that affects the peripheral nerves and/or nerve roots, with increased endoneurial inflammatory leukocytes infiltration and elevated levels of proinflammatory cytokines including IFNγ resulting in axonal demyelination and/or degeneration." (PMID 29615658, 2018). "Also type II IFN/IFNγ was found to remarkably enhance the production of IL-6 by neutrophils treated with R848, further highlighting the capacity of these cells to fully respond to the interferon-induced signals during viral and autoimmune diseases." (PMID 26790609, 2016).
autoimmune disease (continued). "Thus, further work will be necessary to determine whether a feedback loop exists between BAFF-producing neutrophils and IFNγ-producing CD4+ T cells in the recruitment of neutrophils in autoimmune disease." (PMID 25010693, 2014). "The secretion of interferon-gamma (IFN-γ), a pivotal regulator in mediating immune responses against intracellular pathogens and a contributing factor in autoimmune disease mechanisms, is induced by the progression of CD4+ T cells towards TH1 differentiation." (PMID 40230836, 2025). "Although autoimmune diseases exhibit a wide range of pathophysiological mechanisms, common inflammatory markers such as IL-6, TNF-α, and interferon-gamma (IFN-γ) play a role in both autoimmunity and neuroinflammatory processes." (PMID 40002916, 2025). "Nonetheless, interferon gamma (IFNγ), known to induce CD64 expression, plays a pivotal role in the immune regulation of viral and bacterial infections, cancer, and autoimmune diseases." (PMID 38510238, 2024). "Furthermore, the authors showed that anatomically distinct fibroblast subsets with differential IFNγ responses are the key determinants of body-level patterns of lesions in vitiligo, highlighting dFB subpopulations as therapeutic targets for vitiligo and other autoimmune diseases." (PMID 39213029, 2024). "The most common rheumatic and autoimmune disease was SLE (25.7%), followed by RA (24.3%), adult-onset immunodeficiency with anti-interferon gamma autoantibody (12.2%), and pemphigus vulgaris (10.8%)." (PMID 36447248, 2022). "As a typical organ-specific autoimmune disease, we further investigated the levels of MAFTRR and IFNG in the thyroid tissues." (PMID 34869781, 2021). "Some studies of autoimmune diseases have reported that MSC-EVs drive a shift from Th1 toward Th2 cells and rebalances Th1/Th2 cells by downregulating proinflammatory cytokines TNFα and IFNγ and upregulating anti-inflammatory cytokines IL-10 or IL-4." (PMID 34447855, 2021). "In line with this assumption, we showed that also in T cells from patients with autoimmune diseases, PL led to reduced expression of the T cell activation markers CD69 and CD25 and diminished production of IFNγ and IL-2." (PMID 32595640, 2020). "Interferon-gamma (IFN-γ) is a pleiotropic cytokine involved in antiproliferative, pro-apoptotic, antitumor, autoinflammatory, and autoimmune diseases." (PMID 33207669, 2020). "The importance of IFNγ in driving human ASC commitment and differentiation in the context of autoimmune disease is discussed." (PMID 31090539, 2019). "As an autoimmune disorder, celiac disease likely influences PRES through similar inflammatory mechanisms documented in other autoimmune conditions, where endothelial dysfunction occurs through cytokine activation (TNFα, IL‐1, and IFNγ)." (PMID 40114993, 2025). "Interestingly, T-cells from patients with autoimmune diseases exhibit CTSL-dependent complement hyper-activation and IFNγ production." (PMID 38542346, 2024). "Overexpression of specific pro-inflammatory cytokines such as interleukin (IL)-12 and interferon-gamma (IFN-γ) has been reported in SMI, as in autoimmune diseases, and may offset the immunosuppressive state induced by sepsis." (PMID 36913434, 2023). "IFNγ can be produced by innate (NK, NKT, antigen-presenting cells, neutrophils) and adaptive (CD4+, CD8+, B) immune cells and is often elevated in patients with autoimmune diseases and infections with respiratory viruses such as SARS-CoV-2." (PMID 35159372, 2022). "The IS formation stimulates the differentiation of naïve T cells to antigen-specific CD4+ T cells (Th1 and Th17 cells) that induce production of inflammatory cytokines such as TNF-α, IFNγ, and IL-17 in delayed-type hypersensitivity (DTH) and autoimmune diseases." (PMID 36381196, 2022). "Furthermore, in T cells from patients with different autoimmune diseases PL inhibits the expression of the T cell activation markers CD69 and CD25 as well as production of IFNγ and IL-2." (PMID 32595640, 2020).
autoimmune disease (continued). "It has been reported that α-GalCer stimulation can induce iNKT cells to produce both anti-inflammatory cytokines (e.g., IL4, IL13, and IL10) and pro-inflammatory cytokines (e.g., IFNγ, TNFα, and IL17), ultimately determining the outcome of autoimmune diseases such as EAE." (PMID 30766446, 2019). "Interferon-gamma (IFN-γ) is an important mediator of type I immune response and has antiviral, immunoregulatory and anti-tumor properties, plays a wide range of roles in inflammation and autoimmune diseases." (PMID 31870349, 2019). "This change in the balance of IFNγ to IL-10 has been observed in other autoimmune diseases, but has not been previously reported for AIR." (PMID 30271775, 2018). "Notably, while atopic diseases are dominated by production of TH2 cytokines, such as IL-4, IL-5, and IL-13, autoimmune diseases, such as type 1 diabetes, are dominated by the TH1 cytokines IL-2 and interferon gamma (IFN-γ)." (PMID 26557247, 2014). "Th1 cytokines (IFNγ and IL12) are believed to play an important role in the induction of cell-mediated autoimmune disease whereas Th2 cytokines (IL4) promote primarily antibody-mediated autoimmune disease." (PMID 25614713, 2014). "Our recent research on MS disease (article in press) confirms these data, by showing that a sexual dimorphism in autoimmune diseases is the result of different pathways that regulate the Th cell network homeostasis: IL6 pathways in women and IFNγ pathways in men." (PMID 23148571, 2012). "Compared with men, women are more likely to develop autoimmune diseases, which may be related to developing more robust type 1 T-helper (Th1) responses, as females’ naïve CD4+ T cells produce higher levels of type II interferon IFNγ than male T cells." (PMID 37759496, 2023). "In addition, several studies have documented the importance of GM-CSF and the Th17-related cytokines IL-23 and IL-17 for induction of inflammatory and autoimmune disease when IFNγ is lacking." (PMID 29352287, 2018). "However, recent studies suggest that interferon gamma may have both positive and negative effects on the progression of autoimmune diseases depending upon the length of illness, sex of patient, and other factors." (PMID 29257064, 2017). "In addition, EI-03 was also showed to inhibit IFNγ production both in CD4+ T cells and in CD8+ T cells, implying that EI-03 may exhibit a more broad effect in controlling the function of DCs and the differentiation of T cell subsets for treatment of T cell-mediated autoimmune diseases." (PMID 25962726, 2015).